EGFR (epidermal growth factor receptor)
Diseases named in the same sentence as EGFR in open-access papers (continued):
Sharing a sentence is not in itself a finding about the gene and the disease.
tumor (continued). "To test whether EGFR tends to be dominant (i.e., ‘self-sufficient’) and has less co-drivers across tumors compared to other LUAD drivers, we developed a “driver dominance score”, which measures the number of co-occurring drivers for each defined driver gene per tumor." (PMID 29335443, 2018). "Different EGFR signaling output pathways, such as the mitogen-activated protein kinases (MAPK) and the phosphoinositide 3-kinase/Akt pathway, result in cell proliferation, migration and modulation of ion channels which may contribute to tumour invasion, metastasis and progression." (PMID 29552307, 2018). "Therefore, tumor response to third-generation EGFR-TKIs was not evaluated." (PMID 30526536, 2018). "However, in patients with EGFR wild-type, or in patients with unknown EGFR status and without EGFR-TKI treatment history, the overall survival was better for patients who received main tumor resection (P = 0.003)." (PMID 29435191, 2018). "Although tumor classification might increase efficacy and diminish the side effects of new therapies, only RAS mutation status is used routinely as a negative predictive marker to avoid treatment with anti-EGFR agents in patients with metastatic CRC." (PMID 30662905, 2018). "However, a subset of the patients develop resistance that is independent of the EGFR pathway, and multiple resistance mechanisms may co‐exist because of tumour heterogeneity." (PMID 29848757, 2018). "Another explanation might be that the EGFR shRNA used in our experiment was not efficient enough to completely disappear EGFR expression, thus even just a litter remaining EGFR might contribute to Lycorine’s inhibition on tumor growth in the shEGFR xenografts." (PMID 30016965, 2018). "Therefore, the value in testing tumor EGFR T790M in negative plasma patients should be recognized." (PMID 30444875, 2018). "However, we observed different patterns of mRNA expression in these markers toward the higher grades of differentiation, in which MSI1 expression had a direct and constant trend toward the well-differentiated tumors but there was no trend in EGFR expression in the case of tumor differentiation." (PMID 30202417, 2018). "We demonstrate that TUSC3 reduced tumor cell viability and enhanced apoptosis, an effect which may be in part attributed to the ability of TUSC3 to inhibit phosphorylation and down-stream signaling of the EGFR together with additional oncogenic pathways including ERK1/2, hypoxia and Wnt signaling." (PMID 29156678, 2017). "Moreover, tumor-synthesized VEGF is an important immunosuppressive cytokine for eluding immunosurveillant cells (e.g., NK cells, T cells, and so on), and MET and EGFR are also strong therapeutic target candidates in numerous cancers, including those of the lung and colorectum." (PMID 28388297, 2017). "Thus, it appears reasonable to assume that the clinical efficacy of EGFR antagonist treatment may not be based on direct effects on the tumor, but may also be in part based on indirect effects." (PMID 28970798, 2017). "Similarly, we reported a striking example of how tumor heterogeneity between individual metastases at the time of acquired resistance can lead to mixed response and treatment failure in a CRC patient following acquired resistance to the anti-EGFR antibody cetuximab." (PMID 28431544, 2017). "Based on our results, we hypothesize that tumor cells, driven by autocrine GAS6, activate the TAM‐RSK‐dependent survival pathway during the initial steps of tumorigenesis and secondarily switch to a proliferation mode by activation of the MET and/or EGFR‐dependent SRC‐AKT pathway." (PMID 28675785, 2017).
tumor (continued). "The increased survival and long-term duration of response seen in many patients after short treatment with nimotuzumab, suggest that blocking EGFR signaling and inhibiting tumor cell proliferation might not be the only mechanisms of action underlying the efficacy of this antibody." (PMID 28674498, 2017). "In addition, our data also showed that EGFR, HER3 and HER4 genes were more likely to be amplified in the patients with early-stage tumors, suggesting that these aberrations may be early-stage genetic events, contributing to tumor initiation and tumorigenesis." (PMID 29190914, 2017). "An explanation for the positive response to EGFR-targeted inhibition in EGFR-negative tumor cells in vitro or tumor tissue specimens may be due to the dynamic nature of receptor tyrosine kinases protein stability, shuttling between cytosol and membrane as well as membranous anchoring and cleavage." (PMID 28199979, 2017). "In addition, BRAFV600E mutations are more frequently observed in tumours in the right-sided colon than in tumours in the left-sided colon and rectum, and are prognostic biomarkers in CRC and could be potential predictive biomarker for anti-EGFR antibody treatment in pretreated mCRC." (PMID 28972961, 2017). "However, EGFR signaling alone may not be sufficient to potently drive tumor growth since cetuximab therapy does not provide benefit to most patients and, when useful, clinical benefit may not be long-lasting." (PMID 28723928, 2017). "In addition, the authors also recognized that this finding could not be directly employed to the patients who receive third generation of EGFR TKIs (eg., Osimertinib, AZD3759), which has been reported to effectively penetrate the blood-brain barrier and display anti-tumor activity in the brain." (PMID 28881820, 2017). "However, we have hypothesized that the induction of apoptosis and the reduction of HCT116 cell proliferation induced by MAG-EPA might be explained by a reduced activation of the VEGFR and EGFR pathways, which is correlated with a downregulation of AKT signaling in tumor homogenates." (PMID 28869531, 2017). "More recent ASCO guidelines have expanded to recommend tumor testing for mutations in KRAS exons 3 (codons 59 and 61) and 4 (codons 117 and 146) as findings from recent Phase II and III trials indicated patients with these mutations also will not benefit from anti-EGFR therapy." (PMID 29202108, 2017). "In this study, we characterized the molecular mechanism underlying the anti-tumor activity of ENb-TRAIL and evaluated its therapeutic efficacy in various cell lines from different cancer types which are inherently non-responsive to EGFR and DR4/5 targeted monotherapies." (PMID 28572590, 2017). "Indeed, both our in vitro and in situ analyses show that EGFR lacking tumor cells (e.g. DLD1) may be responsive to EGFR inhibition." (PMID 28199979, 2017). "We hypothesized that NK cells in combination with cetuximab could enhance the cytotoxic effects of cetuximab in EGFR+ RASwt/mut BRAFmut CRCs, besides NK cell natural cytotoxicity can mediate anti-tumor activity on EGFR- CRCs that do not respond to anti-EGFR therapy." (PMID 27314237, 2016). "In humans, the hot-spot mutations were found to result in an increased USP8 protein expression, clustering to the nucleus, that correlated in some publications with an increase in EGFR expression in the tumour tissue, while other studies could not confirm this correlation." (PMID 28005997, 2016). "However, in contrast to the Cbl Tyr371 mutants, Cbl Y368F does not promote focus formation in our assays nor does it compromise EGFR ubiquitination in cells and previous work has also shown this mutant does not form colonies in soft agar assays nor promote tumour growth in nude mice." (PMID 27609087, 2016).
tumor (continued). "These germline alterations could have a crucial role in determining how a tumor responds to EGFR-TKIs; however, few studies (none from Latin America) have examined the clinical usefulness of detecting BIM deletion polymorphisms and its relation with clinical characteristics in EGFR positive NSCLC." (PMID 27926478, 2016). "However, recent pre-clinical and clinical data suggest that EGFR inhibition might not improve tumor control and response especially to CRT." (PMID 27015558, 2016). "Constitutive activation of PI3K pathway by PTEN mutation/loss or PIK3CA mutation could render tumor cells independent of RTKs for malignant transformation and maintenance, which leads to resistance to HER2-targeted therapies in BC and EGFR-targeted therapies in glioma." (PMID 27484095, 2016). "Similarly, single inhibition of EGFR could only delay xenograft tumor growth, but not inhibit xenograft tumor growth." (PMID 27105537, 2016). "Additionally, we found that anti-VEGF and EGFR antibodies could not only reduce CRC cells proliferation and invasion in vitro, but also inhibit the tumor growth and angiogenesis in vivo mainly through prohibiting the activation of AKT and ERK signaling pathways." (PMID 27729020, 2016). "Thus, the C. vasculum compound 1 binds to IGF-1Rβ but not InsR or EGFR in NSCLC cells, and both compounds 1 and 2 impair IGF-1Rβ phosphorylation and cause IGF-1Rβ degradation thereby impairing oncogenic signaling in tumor cells resulting in prominent cell death." (PMID 27384680, 2016). "Recently, we tested the potential anti-tumor effect of the recombinant sEGFR in NSCLC cell lines, demonstrating that the sEGFR is capable of inhibiting the tumor cell proliferation and the cell migration in a model without mutations in the TK domain of the EGFR." (PMID 27104520, 2016). "Although the status of EGFR and K-ras mutations has been proposed to guide patient selection for anti-EGFR TKI therapy, the majority of EGFR and K-ras mutations are evaluated only in primary tumors because tumor tissue from the metastatic site is not always available." (PMID 27070580, 2016). "Moreover, to further validate the utility of EGFR and EpCAM for efficient CTCs isolation, we explored FGFR as an example of a marker expressed at low percentages in almost all tumour cell lines checked, which could represent a minority tumour subpopulation." (PMID 27711186, 2016). "However, agents targeting EGFR or mTOR did not elicit anti-tumor responses in the BD-138T PDCs." (PMID 27438149, 2016). "However, to the best of our knowledge, there have been no reports comparing tumor response after TKI therapy between uni-dimensional and volumetric assessment in terms of prognostic factors in patients with adenocarcinoma containing an EGFR mutation." (PMID 26984681, 2016). "To determine whether the regression in tumor growth by purified crocetinic acid is due to inhibition of proliferation, apoptotic cell death or both, we first determined the expression of proliferating cell nuclear antigen (PCNA) as well as that of phosphorylation of EGFR and Akt." (PMID 26317547, 2015). "Furthermore, we confirmed that individual tumor nodules from one tri-transgenic animal might or might not contain human EGFR and if they did not, they still contained p-ERK, implying expression of Kras." (PMID 26047463, 2015). "However, the enhanced oncogenic properties of the mutant EGFR MCF10A cells did not lead to tumour formation in nude mice suggesting that EGFR activation is not sufficient for tumourigenicity in MCF10A cells and a second (or more) genetic alteration is required." (PMID 25969993, 2015). "Finally, these high doses of erlotinib may penetrate the blood-brain barrier and induce tumor shrinkage in EGFR-mutant brain metastases, which are usually not tractable by standard dosing of erlotinib." (PMID 26540572, 2015).
tumor (continued). "The intratumoral heterogeneity of EGFR expression in GBM may ultimately limit the clinical utility of therapies such as TKIs, antibody-based therapies, and RNA-based therapies, because it will not be possible to target every single neoplastic cell in the tumor population." (PMID 25688333, 2015). "Similarly, we could demonstrate that GS-cells with retained EGFR amplification proliferated much faster in vivo than GS-cells from the same primary tumor without EGFR amplification." (PMID 26136784, 2015). "Additionally, EGFR levels did not correlate with the histology of the original tumor." (PMID 26526352, 2015). "Some tumor nodules appear to contain both Kras and EGFR transgenic RNAs, but we could not determine unequivocally whether this means that a few tumors expressed both oncogenes or that multiple tumors may have grown too closely together to separate during macrodissection." (PMID 26047463, 2015). "When certain mutations that may be present in tumours occur, especially in codons 12 and 13 of the KRAS gene, protein activation takes place regardless of the presence of EGFR, which is the target of some drugs for the treatment of this type of cancer, such as panitumumab and cetuximab." (PMID 26557880, 2015). "With the limitations of a comparison between different experiments, one could conclude that the dual inhibition of EGFR and ErbB-receptor shows no larger effect on the prolongation of tumour growth in the three models treated in both experiments compared to the EGFR-TK inhibitor erlotinib." (PMID 25444177, 2014). "Indeed, FoxO3A, which is a well-known tumor suppressor gene, has emerged as a key downstream effector of various drugs used in tumor treatments, such as p38 inhibitors, cisplatin, paclitaxel, doxorubicin, imatinib, PI3K-Akt inhibitors, EGFR/HER2 inhibitors, and ionizing radiation." (PMID 25208626, 2014). "To evaluate whether increased TGF-β and PGE2 production by EGFR inhibitor is detected in a broad range of epithelial tumors or just restricted to the SCC cell line Sa-3, we evaluated these cytokine production in several tumor cell lines pretreated with EGFR TKI." (PMID 25240937, 2014). "In vitro binding and anti-tumor activity of free and AvidinOX-anchored biotinylated antibodies were evaluated on a panel of tumor cell lines of different origin and exhibiting different EGFR expression (high A431, medium H1299, low A549 or none SKMel28) and oncogenic pathways." (PMID 25238453, 2014). "If MMP-9 is playing a major role in the activation of Neu1 sialidase in complex with EGFR as our data suggest, logistically Snail in inducing MMP-9 in ovarian A2780 cancer cells may be the molecular mechanism(s) by which the Snail-MMP signaling axis functions in tumor neovascularization." (PMID 26932374, 2014). "Thus, the elevated EREG expression in TSC tumor cells was not accounted for by the EGFR signaling." (PMID 24748662, 2014). "Furthermore, as both EGFR and cMet are major oncogenic proteins in NSCLC with major contributions to tumor angiogenesis and contact-inhibition, we focused our efforts on determining whether EGFR and/or cMet mechanistically support phenotypic distinctions in monoclonal tumor cells." (PMID 25272226, 2014). "Of the seven AA3 tumors, three contained EGFR amplification with monosomy 10 or CDKN2A/B deletion, a pattern more typical of GBM than ALGG suggesting that these tumors may in fact be more clinically aggressive than typical AA3s or under-sampled with respect to the overall features of the tumor." (PMID 25257301, 2014).
tumor (continued). "Potential differences in tumour phenotypic expression may be exploited to help stratify and in personalisation of therapy as elegantly exemplified by clinical PET studies with [11C]erlotinib, a tyrosine kinase inhibitor of epidermal growth factor receptor (EGFR)." (PMID 25202719, 2014). "The low rates of EGFR and KRAS mutations may reflect a higher rate of false-negative results due to the low tumor cell percentage in proportion to non-neoplastic cells in these lymph nodes, although areas of high tumor cellularity were specifically selected for DNA isolation." (PMID 23935846, 2013). "However, subsequent studies have shown that EGFR-negative tumours may also benefit from cetuximab therapy." (PMID 23356214, 2013). "If a tumor is positive for a KRAS mutation, no further molecular testing is required, and treatment recommendations will focus on chemotherapy because tumors harboring somatic mutations in KRAS, which encodes a GTPase downstream of EGFR, display greater resistance to these targeted drugs." (PMID 23341890, 2013). "As the role of Cbl-b in non-hematopoeitic cell systems has not been investigated in detail and activation of EGFR is known to contribute to chemoresistance in epithelial cancers, the present studies examined the relationship of Cbl-b and EGFR in the modulation of tumor cell sensitivity to 5-FU." (PMID 24351824, 2013). "a tempting approach involving targets that are not in cancer cells is to combine anti-EGFR agents with drugs that may enhance the immune system response against the tumor; for example, with an anti-cytotoxic T lymphocyte antigen 4 (anti-CTLa-4) antibody such as ipilimumab." (PMID 23637683, 2013). "Experiments using pharmaceuticals targeted to the proteins encoded by these two RNAs, gefitinib for ERBB (epidermal growth factor receptor) and trastuzumab for ERBB2 (HER2/Neu) revealed that the upregulated ERBB2 was a critical secondary adaptation driving tumor growth but not ERBB." (PMID 23050958, 2012). "Interestingly, recent results from clinical trials involving nimotuzumab, a new anti-EGFR monoclonal antibody, have reported to have lesser or no skin toxicity which has been postulated to be secondary to selective inhibition for tumor cell EGFR phosphorylation only while sparing the skin." (PMID 22997576, 2012). "However, neither this nor our study found any connection between EGFR expression and tumor stage." (PMID 22475688, 2012). "Similar to other antigens (CD33, Her2, EGFR) which are used as therapeutic targets and that are not tumor cell-specific, first in men studies with novel drugs targeting such new target structures have to be carefully performed, and it has to be determined whether a safe therapeutic window exists." (PMID 22879978, 2012). "Besides inducing tumor cell proliferation, survival, migration, and drug resistance, these alterations trigger changes in the tumor microenvironment, tumor angiogenesis in particular, via upregulation of VEGF as well as deregulation of other molecules including EGFR and COX2." (PMID 21876693, 2012). "Taking all of this information into account, we speculate that ROCK1 is likely to be overexpressed in tumor tissues, and that it controls tumor invasion by a negative feedback system, because of the presence of excessive EGFR stimulation and the subsequent ROCK response in cancer cells." (PMID 21722395, 2011). "Moreover, patients with tumours exhibiting higher EREG or AREG expression had significantly longer PFS, suggesting that these tumours were EGFR dependent and were therefore particularly sensitive to the inhibition of the ligand–receptor interaction by anti-EGFR mAb." (PMID 21139621, 2010). "Furthermore, we found that even in a tumor type such as NSCLC, which has previously been reported to have a prevalence of only 20% of patients having any CTCs, we were able to capture at least one CTC and quantitate EGFR expression in blood samples from 24 out of 34 patients we evaluated." (PMID 20838621, 2010).